RPSAP18 (ribosomal protein SA pseudogene 18)
Synonyms: RPSA_4_107
Gene: Processed pseudogene on chromosome 1 (160,266,340 to 160,267,225, reverse strand). Ensembl gene ENSG00000224261.
Diseases named in the same sentence as RPSAP18 in open-access papers:
RPSAP18 is named in the same sentence as 1 disease in open-access papers, as found by Europe PMC text mining. Sharing a sentence is not in itself a finding about the gene and the disease.
RPSAP18 shares sentences with these, for which no sentence is quoted: skin cutaneous melanoma (1 paper).